MMP1 (matrix metallopeptidase 1)
Diseases named in the same sentence as MMP1 in open-access papers (continued):
Sharing a sentence is not in itself a finding about the gene and the disease.
breast carcinoma (continued). "Higher level of MMP1 mRNA in breast cancer tissue was identified compared with matched normal tissues." (PMID 29207651, 2017). "Its role in clinical breast cancer patients remains to be determined but our data suggest that indeed, MMP-1 is increased in human breast cancer." (PMID 29387062, 2017). "Haplotype analysis of MMP1 and MMP3 genes present on chromosome 11q was performed to calculate the combined effect of MMP1–1607 1G/2G and MMP3–1171 5A/6A polymorphisms on breast cancer." (PMID 28961241, 2017). "Our results suggest that MMP1–1607 1G/2G, MMP3–1171 5A/6A and MMP9–1562 C/T gene polymorphisms have synergistic effect on breast cancer." (PMID 28961241, 2017). "Taken together, the expression status of MMP1 is a significant prognostic indicator and a potential drug target for breast cancer." (PMID 29207651, 2017). "First, we found that both protein and mRNA levels of MMP1 expression were significantly higher in breast cancer tissues." (PMID 29207651, 2017). "Association of the MMP1–1607 1G>2G, MMP3-1171 5A>6A and MMP9-1562 C>T genotypes with breast cancer susceptibility and clinicopathological characteristics." (PMID 28961241, 2017). "In this study, we found that MMP1 upregulation in breast cancer is associated with worse overall survival (OS) and recurrence free survival (RFS) in breast cancer patients after systematic therapy." (PMID 28334049, 2017). "Obviously, we found an elevated expression of MMP-2 and MMP-9 in MCF-7, A549 and H1793, while MMP-1 expression was only observed in breast cancer cell line." (PMID 28915603, 2017). "In the present study SNPs of MMP1, MMP3 and MMP9 genes were correlated with clinicopathological features for their association in breast cancer progression and susceptibility." (PMID 28961241, 2017). "Previous studies suggest that Cdc25A can increase Foxo1 stability, while Foxo1 can enhance transcription of MMP1, leading to enhanced breast cancer cell metastasis." (PMID 28334049, 2017). "MMP1 elevation can also promote the local growth and the formation of brain metastases of breast cancer cells." (PMID 28334049, 2017). "Genotype and allele frequencies distribution for MMP-1, MMP-3 and MMP-9 gene polymorphisms in controls and breast cancer subjects." (PMID 28961241, 2017). "Knockdown of MMP1 inhibited the growth and invasive ability of breast cancer cells in vitro, and also attenuated brain metastasis and lung metastasis in vivo." (PMID 28334049, 2017). "In combination with our findings, we infer that MMP1 is one of the downstream effectors of Slug in modulating chemosensitivity of breast cancer." (PMID 28334049, 2017). "In data set GSE10797, we observed significant downregulation of EFEMP1 and upregulation of MMP1 in stromal cells of 28 breast cancer patients compared with stromal cells from 5 normal individuals who received reduction mammoplastic surgery." (PMID 27468688, 2016). "By analyzing microarray data of in-house generated control and LASP1-depleted MDA-MB-231 breast cancer cells, we observed downregulation of MMP1, -3 and -9 upon LASP1 depletion." (PMID 27588391, 2016). "It is well known that MMP1 promotes the invasion and metastasis of many cancers including lung cancer, breast cancer, and colorectal cancer." (PMID 27391090, 2016). "This evidenced that PAR1 activity contributed to LEC migration and CCID formation, which was stimulated by RELA/NFKB1 - MMP1 signals generated in MDA-MB231 breast cancer spheroids." (PMID 26513020, 2015). "Together, these studies lead to identification of a novel pathway involving EREG and MMP-1 that contributes to the formation of early stage breast cancer." (PMID 26215578, 2015). "A recent study shows a correlation between MMP-1 expression and circulating breast cancer tumor cells and a relationship between MMP-1 expression and high tumor cell proliferation." (PMID 25664615, 2015).
breast carcinoma (continued). "Our analysis of publicly available clinical and cellular expression data revealed that low levels of MMP-1, -2, -9, and -14 are important for breast cancer survival." (PMID 28721370, 2015). "It was shown, in a xenograft orthotopic cancer mouse model, that RKIP inhibited breast cancer metastasis by partly inhibiting the positive regulator of the MMP1 transcription." (PMID 26308852, 2015). "Noteworthy, the MMP1-PAR1 axis works in several ways: not only from tumour to lymphatics but also from stroma to tumour, because stromal MMP1 was shown to activate PAR1 in breast cancer cells thereby inducing cancer cell migration and invasivity." (PMID 26513020, 2015). "Curcumin and its derivatives have been found to inhibit the proliferation of breast cancer (BC) cell lines and by downregulation of matrix metalloproteinase-1 (MMP-1) expression." (PMID 26180591, 2015). "It has been reported that MMP-1 increased migration and invasion of breast cancer cell due to slaving and activating the protease activated receptor-1 (PAR-1)." (PMID 26313265, 2015). "We describe that in MDA-MB231 breast cancer cells NF-κB activity constituted MMP1 expression, which in turn activated PAR1 signalling in adjacent LECs." (PMID 26513020, 2015). "In another study involving a mammary fat pad rat xenograft model, expression of MMP-1 in stromal fibroblasts was shown to confer high invasion potential to breast carcinoma cells." (PMID 26306560, 2015). "Recently, the EMT-inducer ZEB1 was not only described as initiator of metastasis, but also to induce osteoclast formation and to inhibit osteoblast differentiation by regulating MMP1 expression in an in vitro system of breast cancer bone metastasis." (PMID 25973542, 2015). "Expression of some MMPs correlated with FOXC1 expression, such as MMP7 in breast cancer and MMP1, MMP2, MMP7, and MMP9 in hepatocellular cancer." (PMID 24889262, 2014). "The AP1-complex members c-JUN and c-FOS are involved in the activation of the promoter of MMP1 in MDA-MB-321 breast cancer cells secondary to the activation of ZEB1, a transcription factor involved in EMT." (PMID 24586640, 2014). "In the MCF-7 and MDA-MB-231 human breast cancer cell lines, we showed that Pit-1 regulates MMP-1 and MMP-13." (PMID 25527274, 2014). "In the present study we also found positive correlations between global expression (score values) of Pit-1 and either MMP-1 or MMP-13 expression in human primary breast carcinomas." (PMID 25527274, 2014). "Increased tumor expression of MMP-1, MMP-2, MMP-7, or MMP-9 in lung cancers, and increased expression of MMP-1 and MMP-9 in breast cancer is associated with poor patient survival." (PMID 25491880, 2014). "In breast cancer patients, expression of Pit-1 was found to be positively correlated with the presence of both MMP-1 and MMP-13." (PMID 25527274, 2014). "MMP-1 is often upregulated in breast cancer, especially in basal-type tumors, and seems to be critically involved in metastatic dissemination." (PMID 25527274, 2014). "Given that these MMPs have been related to breast cancer metastasis, we explored the effect of Pit-1 overexpression and MMP-1 or MMP-13 knockdown in an SCID mouse xenograft tumor model." (PMID 25527274, 2014). "Overexpression of UEV1A alone in MDA-MB-231 cells is sufficient to activate NF-кB, which in turn upregulates the MMP1 expression to enhance breast cancer cell metastasis." (PMID 25022892, 2014). "While most associations were modest, multiple polymorphisms in MMP1 and MMP2 were associated with breast cancer risk overall and with ER+ tumors." (PMID 23696797, 2013). "MMP1 [4 single nucleotide polymorphisms (SNPs)] and MMP2 (2 SNPs) were associated with breast cancer overall." (PMID 23696797, 2013). "MMP-1 is among the “bone metastasis signature” genes identified using human breast cancer cells in a mouse model, and found to be overexpressed in tumor cells of human bone metastases when compared to a human normal epithelial cell line." (PMID 23696795, 2013).
breast carcinoma (continued). "In breast cancer patients, MMP-1 expression has been correlated to primary tumor progression, metastatic potential, and survival." (PMID 25339983, 2013). "MMP1 and MMP2 were associated with many aspects of breast cancer prognosis including unique associations with ER/PR tumor status as well as with survival." (PMID 23696797, 2013). "Elevated MMP-1 and ADAMTS1 expression is associated with increased risk of bone metastasis in breast cancer patients." (PMID 23696795, 2013). "In vivo, MMP-1 was shown to be overexpressed in breast cancer samples, compared to normal breast tissue, and in bone metastasis from breast cancer, compared to brain metastases or normal breast tissue." (PMID 23696795, 2013). "MMP-1 has been shown behave like thrombin, enhancing the migration of highly invasive breast cancer cells through proteinolytic activation of PAR-1." (PMID 23675494, 2013). "MTT assays were used to analyze if MMP-1 reduction affects breast cancer cell proliferation in vitro." (PMID 23217186, 2012). "In fact, in the metastatic process across the axillary lymph node chain in breast cancer, MMP-1 expression by mononuclear inflammatory cells (MICs) from the sentinel lymph node (SLN) was significantly associated with metastatic spread to non-SLNs." (PMID 23300781, 2012). "Our results show that elevated expression of MMP-1 can promote the local growth and the formation of brain metastases by breast cancer cells." (PMID 23217186, 2012). "Short hairpin RNA-mediated stable knockdown of MMP-1 inhibited the invasive ability of MDA-MB 231 variant cells in vitro, and inhibited breast cancer growth when the cells were injected into the mammary fat pad of nude mice." (PMID 23217186, 2012). "δEF1 was also shown to induce MMP-1 expression in MDA-MB-231 breast cancer cells, resulting in osteolytic bone metastasis." (PMID 23285017, 2012). "The addition of an MMP-1 inhibitor in further experiments confirmed that MMP-1 activity can modulate levels of TGFα in culture supernatants of the breast cancer cell lines." (PMID 23217186, 2012). "In this report we provide evidence that elevated expression of MMP-1 contributes to the brain colonizing potential of human breast cancer cells in xenograft models of cancer progression." (PMID 23217186, 2012). "Two variants of the MDA-MB-231 human breast cancer cell line selected for enhanced ability to form brain metastases in nude mice (231-BR and 231-BR3 cells) were found to express high levels of matrix metalloproteinase-1 (MMP-1)." (PMID 23217186, 2012). "In this study, we show that the targeted knockdown of MMP-1 in breast cancer cells with enhanced brain metastatic ability not only reduced primary tumor growth, but also significantly inhibited brain metastasis." (PMID 23217186, 2012). "MMP-1 is often upregulated in breast cancer, especially in basal-type tumours, and is supposed to be critically involved in metastatic dissemination." (PMID 21835023, 2011). "Our results demonstrate MMP-1 positivity both in the nuclei and in the cytoplasm of breast cancer cells and in the stromal cells, often termed as cancer-associated fibroblasts (CAFs)." (PMID 21835023, 2011). "In particular, MMP-1, -9, and -13 are strongly correlated with the incidence of breast cancer metastasis and are potential markers for poor prognosis of invasive breast cancer." (PMID 22174624, 2011). "Prior studies indicate that MMP-1, -2, -8, -9 -10, -11, -12, -13, -15, -19, -23, -24, -27 and -28 promote breast cancer development and tumor progression." (PMID 22174624, 2011). "In this study, we evaluated MMP-1 expression by immunohistochemistry using original tissue sections instead of tissue microarrays, and correlated it with different breast cancer subtypes and with traditional prognostics factors and patient survival." (PMID 21835023, 2011). "One important finding of the present study is the significantly different MMP-1 expression in stromal cells of different breast cancer subtypes." (PMID 21835023, 2011).
breast carcinoma (continued). "PAR-1 can also be proteolytically cleaved and activated by matrix metalloprotease-1 (MMP-1) in breast cancer cells." (PMID 21378407, 2011). "The expression of MMP-1 is characteristic for many types of malignant tumours, including breast cancer." (PMID 21835023, 2011). "The most important finding of the present work is that the MMP-1 expression of tumour cells carries an independent prognostic value in breast cancers." (PMID 21835023, 2011). "MDA-MB-231 breast cancer cells responded to the artesunate treatment (lanes labeled with “+”) with a transient (3 and 5 h) reduction of MMP-1 activity released into fresh serum-free medium in comparison to carrier-treated cells (lanes labeled with “−”)." (PMID 21637790, 2011). "We analyzed the amount of the metastasis-related protease MMP-1 secreted into the cell supernatants of artesunate treated human breast cancer cells MDA-MB-231 by Western blots with specific antibodies against MMP-1." (PMID 21637790, 2011). "MMP-1 positivity in stromal cells showed significant differences (p = 0.0129) between breast cancer subtypes." (PMID 21835023, 2011). "Role of MMP1 has been well documented in the establishment of lung metastasis in breast cancer as well for establishment of primary lung cancer." (PMID 21170377, 2010). "Recently, the G protein-coupled receptor, PAR1, has been found to be cleaved by MMP1, which promotes breast cancer migration and invasion." (PMID 19489099, 2009). "In particular, interstitial collagenase (MMP1) has been reported to be involved in the invasion of breast carcinoma." (PMID 19489099, 2009). "MMP-1 and -13 also showed a higher expression of mRNA in grade 3 breast cancer tissue compared to normal breast tissue, but these differences were not statistically significant." (PMID 19531263, 2009). "Significantly higher mRNA expression in breast cancer tissue in contrast to normal breast tissue was detected for MMP-1, -9, -11, -13 and -28." (PMID 19531263, 2009). "In summary, we identified several MMPs (MMP-1, -2, -8, -9, -10, -11, -12, -13, -15, -19, -23, -24, -27 and -28) with a stronger expression in breast cancer tissue compared to normal breast tissue." (PMID 19531263, 2009). "In this study, we evaluated the usefulness of circulating MMP1, MMP8 and MMP13 levels as diagnostic and prognostic markers in breast cancer." (PMID 18366705, 2008). "This study aimed at evaluating plasma levels of MMP1, MMP8 and MMP13 as diagnostic and prognostic markers of breast cancer." (PMID 18366705, 2008). "Western blots clearly showed immunoreactive bands corresponding to MMP-1, -11, -13 and -14 in seven samples from breast carcinomas." (PMID 17848954, 2007). "This has been shown in previous studies where in vivo MMP-1 expression was found in the stromal area along the invasive margin in gastric cancer and breast cancer." (PMID 11953862, 2002). "MMP-1 production has also been found to be up-regulated during cell–cell contact with breast carcinoma cells and bone marrow fibroblasts." (PMID 11953862, 2002). "To further investigate whether the role of SPANXB1 in promoting breast cancer cell extravasation is mediated through MMP1, we conducted rescue experiments." (PMID 40885703, 2025). "Furthermore, we observed that SPANXB1 upregulates the expression of MMP1, which subsequently enhances the transmigration of breast cancer cells across the BBB and accelerates the progression of BCBM." (PMID 40885703, 2025). "Furthermore, MMP1 upregulation was reported to potentiate tamoxifen (TAM) resistance in TAM-resistant MCF-7 breast cancer cells and increase tumor growth of TAM-resistant MCF-7 breast cancer in a xenograft mouse model." (PMID 40214422, 2025). "Notably, the RUNX2 and matrix metalloproteinase 1 (MMP1) axis serves as a new marker for breast cancer diagnosis." (PMID 41511334, 2025).
breast carcinoma (continued). "The ability of rosmarinic acid to inhibit MMP-1, MMP-2, MMP-9, aldose reductase, and CDC25B activity may underlie how rosmarinic acid is able to inhibit the development of breast cancer." (PMID 40176865, 2025). "Taken together, through maintaining and promoting the oncogenic AP-1 activation, PRDX3 may contribute to the activation of AP-1 downstream signaling pathways target MMP-1, that is critical for the malignancy of human breast cancer cells." (PMID 38321552, 2024). "A recent study indicates that activation of the extracellular signal-regulated kinase (ERK) signaling may also result in the MMP1 transcriptional activation in the peroxiredoxin 3 (PRDX3)-overexpressed breast cancer cells." (PMID 39590789, 2024). "MMP-1 is also involved in tamoxifen resistance in breast cancer." (PMID 39697341, 2024). "In contrast, the miR-21 expression in the patients was significantly lower than in the controls, indicating that MMP-1 and miR-21 may be potential screening markers for breast cancer." (PMID 37047335, 2023). "According to the status quo of the research of MMP-1 in breast cancer, inconsistent conclusions could be found in these studies mentioned in our discussion." (PMID 37188722, 2023). "Finally, COX2, an enzyme known to synthesize prostaglandins, appears to induce the expression of matrix metalloproteinase-1 (MMP1) in brain metastatic breast cancer cells, therefore inducing permeability of the BBB." (PMID 37190188, 2023). "Interestingly, the MMP8 insulator element impairment leads to a decrease in the pro-invasive enzyme MMP1 and increased MMP8 expression levels, two events that are associated with antitumor activity in breast cancer." (PMID 38017545, 2023). "MMP-1 was also reported to be involved in tamoxifen resistance in breast cancer." (PMID 36741729, 2022). "A negative association between promoter methylation and MMP1 expression levels was also confirmed in tamR and tamS breast cancer patients." (PMID 35267540, 2022). "In the current study, our findings from univariate analysis showed that MMP1 rs1799750 2G allele noncarriers were significantly less linked to poor breast cancer differentiation." (PMID 36009438, 2022). "Furthermore, breast cancer patients with high MMP1 expression exhibited a lower survival ratio compared to those with low expression." (PMID 35267540, 2022). "Furthermore, malignant microcalcifications that remain even after NAC contain larger hydroxyapatite particles, which upregulate MMP-1 and promote the aggressiveness of breast cancer by decreasing the elasticity of the extracellular matrix." (PMID 36513704, 2022). "MMP-1 has been shown to play a role in breast cancer brain metastasis." (PMID 36741729, 2022). "A study of two variants of the MDA-MB-231 human breast cancer cell line (231-BR and 231-BR3) xenografted into the mammary fat pad and blood of nude mice demonstrated that MMP-1 facilitates local growth of breast cancer cells and the formation of brain metastases." (PMID 36291773, 2022). "Although MMP1 is one of the best-studied MMPs, there are not enough studies to develop a strong attitude concerning associations between SNPs and clinical breast cancer features." (PMID 36009438, 2022). "Third, four hub genes that could have important key functions in tumor growth in breast cancer, MMP1, SDC1, CD24, and SPP1, were identified using GEO and TCGA public datasets as potential prognostic biomarkers." (PMID 35037689, 2022). "MMP1 is a gene that drives breast cancer cells to become tamR." (PMID 35267540, 2022).